SLIT2 (slit guidance ligand 2)
Diseases named in the same sentence as SLIT2 in open-access papers (continued):
Sharing a sentence is not in itself a finding about the gene and the disease.
prostate carcinoma (6 papers, 2011 to 2025). A carcinoma that arises from epithelial cells of the prostate gland. "PSP94 is a suppressor of tumor growth and metastasis; SLIT2 inhibits prostate cancer cell proliferation and invasion; and CDKN2A is a critical tumor suppressor gene." (PMID 28410242, 2017). "In fact, CDKN2A, ADRB2, CDH1 and SLIT2 were reported to be suppressed by EZH2 in prostate cancer cells and were also targeted by EZH2 in at least one prostate cell line in our ChIP sequencing analysis." (PMID 27835578, 2016). "SLIT2 is downregulated in prostate cancer by epigenetic mechanisms and represents a potent prognostic biomarker that merits further evaluation in large patient cohorts." (PMID 22191037, 2011). "SLIT2 is a representative target of EZH2 in prostate cancer and its promoter is occupied with EZH2." (PMID 25537508, 2015). "Although this pattern of overexpressed EZH2 and depressed SLIT2 is observed in other cancer types, the combination of these two may serve as a pertinent duo-panel of characteristic biomarkers for prostate cancer prognosis." (PMID 22641253, 2012). "Overexpression of SLIT2 inhibits prostate cancer cell proliferation and invasion." (PMID 22191037, 2011). "Also, PSP94, SLIT2 and CDKN2A are downstream targets of EZH2 in prostate cancer that mediates tumorigenesis and metastasis." (PMID 28410242, 2017).
colon carcinoma (5 papers, 2010 to 2023). "In this study, we employed two complementary mouse models of intestinal cancers: a genetically engineered spontaneous small intestinal adenoma mouse model and a carcinogen-induced colon carcinoma model to analyze the expression and function of Slit2 in the development of intestinal cancers." (PMID 25605242, 2015). "SLIT2 appears to be a candidate for a colon cancer suppressed gene, since it is often inactivated by LoH and hypermethylation and its receptor, ROBO1, has been implicated in colon cancer, although the underlying mechanism of the SLIT-ROBO involved tumor growth remains obscure." (PMID 20187943, 2010). "Additionally, in colon cancer, SLIT2/ROBO1 has been shown to encourage tumor growth." (PMID 38304289, 2023).
depression (5 papers, 2020 to 2025). "An epigenome-wide association study (EWAS) of MDD patients found that altered methylation in the Slit2 locus is associated with late-life depression." (PMID 33613201, 2020). "While SLIT2 is known for its role in axon guidance and has been implicated in depression and anxiety-like behaviors in mice, which are symptoms shared across various psychiatric disorders, our results indicate a cell-type–specific dysregulation in the human cortex." (PMID 40053590, 2025). "Our data in combination with our previous studies have shown that increased permeability of the BBB and damaged neurons caused by overexpression of Slit2 could be underlying causes of depression and anxiety." (PMID 33613201, 2020). "Fourth, only the level of TNF-α was increased in the hippocampus of 23-week-old Slit2-Tg mice, indicating that mild inflammation caused by overexpression of Slit2 could underlie anxiety- and depression-like behavior." (PMID 33613201, 2020). "Of thirteen depression‐associated DRPs, seven proteins including DDC, FGFR2, KIBRA, MED22, OLIG1, RAI1, SLIT2 were upregulated, whereas six proteins including COX3, CRHBP, CSMD1, FSTL1, GRIK4, and LMTK3 were downregulated." (PMID 39373701, 2024). "Studies in rodents found that Slit2 is an axon guidance molecule, and transgenic mice with Slit2 overexpression exhibit depression and anxiety-like behavior." (PMID 39687694, 2024). "Compared with 5-HT KO mice, although no significant changes in monoamine transmitters were observed in Slit2-Tg mice, the mice were able to show coexistence of anxiety and depression." (PMID 33613201, 2020). "Depression-like behaviors in Slit2-Tg mice were also examined in the forced swim test and tail suspension test." (PMID 33613201, 2020). "The results indicate important roles of Slit2 in brain functions and the potential of Slit2-Tg mice as a model of spontaneous depression and anxiety." (PMID 33613201, 2020). "Second, 21-week-old Slit2-Tg mice exhibited increased anxiety- and depression-like behavior compared with WT mice." (PMID 33613201, 2020). "The relationship between Slit2 and depression- and anxiety-like behavior needs to be further investigated and will be the focus of future work in our lab." (PMID 33613201, 2020). "Depression-like behaviors in Slit2-Tg mice were assessed based on the index of sucrose preference, which reflected anhedonia." (PMID 33613201, 2020). "Slit2-Tg mice, thus, display both anxiety and anhedonia, making them a potent animal model in the treatment of forms of depression comorbidly expressed with anxiety." (PMID 33613201, 2020). "We used a 5-min open field test to further evaluate the anxiety- or depression-like behaviors of Slit2-Tg mice." (PMID 33613201, 2020). "Overall, we discovered that 23-week-old Slit2-Tg mice display several anxiety- and depression-like behavioral abnormalities, including decreased weight, anhedonia, impaired hippocampal morphology, and molecular alterations in the brain." (PMID 33613201, 2020). "Our data show that 21-week-old Slit2-Tg mice exhibit symptoms similar to those observed in patients with major depression or anxiety disorders." (PMID 33613201, 2020). "For example, adult transgenic mice constitutively overexpressing human Slit2 in whole-body exhibited increased depression-/anxiety-like behavior alterations assessed by sucrose preference test, open field test and elevated plus maze, with lower body weights compared to wild-type animals." (PMID 37035502, 2023). "These alterations may bring about depression- and anxiety-like behaviors in 23-week-old mature adult Slit2-Tg mice and may provide a spontaneous model for studying mental disorders." (PMID 33613201, 2020). "In particular, these results indicated that the overexpression of Slit2 could be the potential molecular mechanism of depression." (PMID 33613201, 2020).
depression (continued). "Overall, these results suggest depression-/anxiety-like behavior alterations in adult Slit2 transgenic mice, although these results might have been influenced by measurement error." (PMID 33613201, 2020). "All of these results demonstrated that depression- and anxiety-like phenotypes were observed in 23-week-old Slit2-Tg mice, which might be partially due to elevated proinflammatory factors." (PMID 33613201, 2020). "However, there is little clinical evidence that Slit2 is associated with depression, and there is lack of direct experimental and experimental evidence to support this view." (PMID 33613201, 2020).
leukemia (5 papers, 2012 to 2022). A malignant (clonal) hematologic disorder, involving hematopoietic stem cells and characterized by the presence of primitive or atypical myeloid or lymphoid cells in the bone marrow and the blood. "Finally, reduced expression of SLIT2 in murine APL blasts resulted in fatal leukemia associated with increased leukocyte counts in vivo." (PMID 33120864, 2020). "Next, we investigated the effect of the addition of exogenous recombinant hSLIT2 together with the overexpression of ROBO1 or ROBO2 on the biological characteristics of leukaemia cells (magnification effect of SLIT2/ROBO signalling)." (PMID 26608094, 2015). "Loss of normal hematopoiesis is a classical event during human myeloproliferative neoplasias and leukemias where the niche downregulate essential HSPC retention factors as CXCL12, SCF, LepR, Angpt1, Cdh2, Slit2, and TGF-β1 though pro-inflammatory factors secreted by leukemia-initiating cells." (PMID 28111575, 2016).
melanoma (5 papers, 2010 to 2024). A malignant, usually aggressive tumor composed of atypical, neoplastic melanocytes. "Melanoma M4 had also a concomitant missense mutations in SLIT2 (L224F)." (PMID 27095580, 2016). "Among them we identify BIRC3, SLIT2, GBP2, and AFAP1 to be involved in the acquisition of BRAFi resistance in melanoma cell lines." (PMID 32708687, 2020).
non-small cell lung carcinoma (5 papers, 2004 to 2025). A group of at least three distinct histological types of lung cancer, including non-small cell squamous cell carcinoma, adenocarcinoma, and large cell carcinoma. "A recent study reported that methylation in the SLIT2 gene might be a potential biomarker for detecting non-small cell lung cancer and predicting recurrence-free survival, although future studies with a larger sample size are required to confirm these results." (PMID 40508075, 2025). "The aim of the present study was to assess the precise methylation levels of LINE-1, SLIT2, MAL and IGFBP7 in non-small cell lung cancer (NSCLC) using a pyrosequencing assay." (PMID 23381221, 2013).
Obesity (5 papers, 2018 to 2021). Accumulation of substantial excess body fat. "Additional genes involved in pathways closely related to the obesity phenotype highlighted by our analysis as potential candidates that play a role in male mice susceptibility to obesity are Cckar, Sod3, Med28, and Slit2." (PMID 33143653, 2020). "In this case study, we report a novel tetrad of congenital myopia, anisometropia, obesity, and connective tissue abnormalities in a patient with a variant in SLIT2, c.4220A > G (p.D1407G)." (PMID 30111362, 2018). "Here, we report a case of congenital myopia, anisometropia, and obesity in a patient with a SLIT2 point mutation." (PMID 30111362, 2018). "Peptidase M20 domain containing 1 (PM20D1) and Slit2 are two newly identified batokines that improves glucose homeostasis as well as regulate thermogenesis which might be used for the treatment of obesity and obesity associated metabolic disorders." (PMID 33511131, 2020). "These conclusions are limited, as they are derived from a singular case thus far, and there exists the possibility that there are other unidentified variants contributing to aspects of the patient’s phenotype, such as obesity, that may be unrelated to the SLIT2 mutation." (PMID 30111362, 2018). "This further underscores the importance of future studies to shed light on the role of SLIT2 in connective tissue pathophysiology, obesity, and ocular disease." (PMID 30111362, 2018). "Thus, we next examined the effects of obesity on SLIT2 expression in human adipose ECs." (PMID 34660572, 2021).
osteosarcoma (5 papers, 2016 to 2022). A usually aggressive malignant bone-forming mesenchymal neoplasm, predominantly affecting adolescents and young adults. "Studies have also found that the SLIT2/ROBO1 axis promotes the Warburg effect of osteosarcoma by activating the SRC/ERK/c-MYC/PFKFB2 pathway." (PMID 36387908, 2022). "Literature had reported the overexpression of SLIT2 in various cancers, including gastric, colorectal, and osteosarcoma." (PMID 32760720, 2020). "Transposon insertions were found in Srgap2, Enah, Slit2, Slit3, or Robo1 in 24 percent of primary tumors from mice with Sleeping Beauty derived osteosarcoma, further implicating the role of the Slit-Robo pathway in osteosarcoma." (PMID 27966608, 2016). "In addition, Slit2 often promote tumor development in skin cancer, osteosarcoma, and CRC." (PMID 31242633, 2019).
periodontitis (5 papers, 2020 to 2024). An acute or chronic inflammatory process that affects the tissues that surround and support the teeth. "For the first time, this study reported that the SLIT2 overexpression in periodontal tissue intensifies the periodontitis progression and alveolar bone loss possibly via the activation of MAPK pathway." (PMID 32760720, 2020). "This study aims to explore the expression pattern of SLIT2 in periodontitis and its role in disease progression and bone loss." (PMID 32760720, 2020). "Histomorphometric analysis showed 1.3-fold higher periodontitis-induced alveolar bone loss in Slit2-Tg mice compared to wild-type mice." (PMID 32760720, 2020). "Slit2-Tg mice periodontitis exhibited more bone loss and bone destruction in the alveolar crest height than in wild-type mice periodontitis." (PMID 32760720, 2020). "The effect of SLIT2 on inflammation, immune cell infiltration, M1 macrophage polarization, and alveolar bone loss in periodontitis was analyzed extensively." (PMID 32760720, 2020). "RNA sequencing (RNA-seq) of mice PAPT was performed to explore the underlying mechanisms of the regulatory effects of SLIT2 on periodontitis." (PMID 32760720, 2020). "Our results suggest that the SLIT2-induced inflammation-mediated osteoclastogenesis might cause alveolar bone loss in periodontitis." (PMID 32760720, 2020). "However, SLIT2 overexpression aggravated the periodontitis and periodontitis-induced alveolar bone loss." (PMID 32760720, 2020). "The effect of SLIT2 on the infiltration of immune cells, M1 macrophage polarization, osteoclastogenesis, and alveolar bone loss was extensively analyzed in Slit2-Transgenic (Tg) periodontitis mice." (PMID 32760720, 2020). "Moreover, SLIT2 overexpression intensifies the infiltration of leucocytes/macrophages, inflammation, M1 macrophage polarization, osteoclastogenesis, alveolar bone loss, and activation of P-P38 signaling in periodontitis." (PMID 32760720, 2020). "SLIT2 expression was upregulated in periodontitis in both humans and mice, and a higher expression of SLIT2 accelerated the progression of periodontitis." (PMID 34445604, 2021). "Our finding indicates the possible role of activated MAPK pathway in SLIT2-mediated effects on periodontitis." (PMID 32760720, 2020). "We analyzed SLIT2 expression in the human periodontitis-affected gingival tissue and ligature-induced periodontitis (LIP)-affected mice periodontal tissue." (PMID 32760720, 2020). "In this study, we analyzed the role of the higher SLIT2 expression in periodontitis on osteoclastogenesis." (PMID 32760720, 2020). "Our results indicate that the overexpressed SLIT2 in periodontitis aggravates the consequences of the disease, such as the destruction of periodontal tissue and alveolar bone loss." (PMID 32760720, 2020). "In periodontitis-affected gingival-tissue, SLIT2 expression was 4.4-fold higher compared to healthy-volunteers." (PMID 32760720, 2020). "In this study, we unraveled the >4.0-fold upregulation of SLIT2 protein in periodontitis-affected tissue of human and mice compared to healthy tissue." (PMID 32760720, 2020). "The majority of pathophysiological parameters of the periodontitis were affected by SLIT2 overexpression, indicating the vital role of SLIT2 to on periodontitis progression." (PMID 32760720, 2020). "GO enrichment pathway analysis of top 134 differentially expressed mRNAs in periodontitis-affected tissue of Slit2-Tg mice revealed the significant upregulation of MAPK signaling related genes." (PMID 32760720, 2020). "First, we examined the SLIT2 expression in human gingival tissues of 20 periodontitis patients and 20 age and gender-matched healthy individuals." (PMID 32760720, 2020). "Overexpression of SLIT2 in periodontitis escalated inflammation, lymphocyte/macrophage infiltration, M1 macrophage polarization, osteoclastogenesis, alveolar bone loss, and disease progression." (PMID 32760720, 2020).
periodontitis (continued). "More numbers of CD45 positive cells were observed in periodontitis-affected gingival tissue of Slit2-Tg mice compared to wild-type mice." (PMID 32760720, 2020). "SLIT2 intensified the inflammation in PAPT as indicated by higher MVD, and infiltration of leucocytes/macrophages in periodontitis Slit2-Tg mice compared to wild-type mice." (PMID 32760720, 2020). "Slit2-Tg periodontitis mice model unveiled the role of SLIT2 on the escalation of disease pathophysiology." (PMID 32760720, 2020). "Slit2-Tg periodontitis mice showed a 1.3-fold higher CEJ-ABC distance compared to wild-type periodontitis mice." (PMID 32760720, 2020). "In this study, we aimed to analyze the expression pattern of SLIT2 in periodontitis-affected gingival tissue, and the role of SLIT2 on the pathophysiology of periodontitis." (PMID 32760720, 2020). "In this study, we unraveled the higher expression of the SLIT2 in clinical gingival tissues of periodontitis patients." (PMID 32760720, 2020). "In the present study, serum SLIT2 level in periodontitis mice was upregulated by 5.0-fold compared to healthy mice indicating systemic upregulation." (PMID 32760720, 2020). "The SLIT2 protein level in periodontitis-affected human gingival tissue was 4.4-fold higher compared to healthy gingival tissue." (PMID 32760720, 2020). "Our results suggest the possible role of SLIT2/ROBO1 signaling of the pathophysiology of periodontitis via activation of MAPK p38 signaling." (PMID 32760720, 2020). "In this study, we found that both SLIT2 and ROBO1 were upregulated in periodontitis, suggesting the possible role of SLIT2/ROBO1 axis on escalation of inflammation and disease progression in periodontitis." (PMID 32760720, 2020). "In periodontitis, the overexpression of Slit2 may exacerbate inflammation and immune cell infiltration, potentially activating p38/MAPK through the Slit2/Robo1 signaling pathway." (PMID 39768930, 2024). "In addition, Slit-2 is overexpressed in periodontitis and aggravates the inflammatory response, lymphocyte/macrophage infiltration and disease progression." (PMID 35813663, 2022). "Ligature-induced periodontitis (LIP) mice-model was developed in Slit2-Tg and wild-type mice." (PMID 32760720, 2020). "Similarly, CEJ-ABC distance in periodontitis Slit2-Tg mice was 2.3-fold higher compared to healthy Slit2-Tg mice." (PMID 32760720, 2020). "Our study elucidated SLIT2 overexpression in human and mice periodontitis-affected tissue." (PMID 32760720, 2020). "However, the effect of SLIT2 on MAPK signaling in periodontal immune cells during periodontitis is still a mystery." (PMID 32760720, 2020). "Moreover, periodontitis condition upregulates the level of serum SLIT2 in wild-type mice showing the systemic effect of periodontitis." (PMID 32760720, 2020). "A limitation of this study is that we did not analyze which isotope of SLIT2 regulates the pathophysiology of periodontitis and whether ROBO1 is the key receptor for SLIT2-mediated effect on periodontitis." (PMID 32760720, 2020). "The neutrophil and macrophage chemoattractant properties of SLIT2 in periodontitis might be the act of Slit2-N fragment." (PMID 32760720, 2020). "Additionally, the serum of wild-type periodontitis mice showed 5.0-fold higher expression of SLIT2 protein compared to wild-type healthy mice." (PMID 32760720, 2020). "However, the effect of SLIT2 on, the infiltration of leucocytes/macrophages in periodontitis-affected gingival tissue, and regulation of periodontitis-induced inflammatory cascade still need to be investigated." (PMID 32760720, 2020). "However, the expression pattern of SLIT2 in periodontal tissue during periodontitis and its’ role in the pathophysiology of periodontitis is still unknown." (PMID 32760720, 2020). "Our results indicate the upregulation of SLIT2 expression in gingival tissue during periodontitis in human and in PAPT of wild-type mice or Slit2-Tg mice." (PMID 32760720, 2020).
periodontitis (continued). "In this study, we found evident upregulation of SLIT2 in periodontitis-affected human gingival tissue, and PAPT of mice, as well as in the serum of periodontitis mice." (PMID 32760720, 2020). "SLIT2 overexpression upregulated Robo1 and MAPK signaling related factors’ expression in PAPT during periodontitis." (PMID 32760720, 2020). "We further elucidated the higher SLIT2 expression in PAPT and serum of periodontitis mice." (PMID 32760720, 2020). "SLIT2 overexpression did not initiate the periodontitis itself." (PMID 32760720, 2020). "We did not witness the direct effect of SLIT2 on osteoblast function during periodontitis." (PMID 32760720, 2020).